TRIB2 (tribbles pseudokinase 2)
Diseases named in the same sentence as TRIB2 in open-access papers (continued):
Sharing a sentence is not in itself a finding about the gene and the disease.
glioma (continued). "Moreover, elevated coexpression of TRIB2 and MAP3K1 was significantly correlated with a poor prognosis and indicated therapeutic resistance in glioma." (PMID 31318172, 2020). "Moreover, a combined increase in TRIB2 and MAP3K1 was observed in GBM and indicated a poor prognosis of patients with glioma." (PMID 31318172, 2020). "TRIB2 and MAP3K1 could be used as novel therapeutic targets and prognostic biomarkers to evaluate the malignancy and long‐term outcome of glioma." (PMID 31318172, 2020). "Additionally, ROC analysis was performed to evaluate the sensitivity and specificity of TRIB2 and MAP3K1 for the prediction of outcomes in patients with glioma." (PMID 31318172, 2020). "The ROC analysis confirmed that the sensitivity and specificity of TRIB2/MAP3K1 expression were statistically significant, indicating that TRIB2/MAP3K1 expression should be investigated for evaluating the prognosis and therapeutic efficacy in patients with glioma." (PMID 31318172, 2020). "Moreover, co‐overexpression of TRIB2 and MAP3K1 (TRIB2High/MAP3K1High) tended to indicate shorter overall survival than other expression combinations in patients with glioma." (PMID 31318172, 2020). "Overall, our findings suggest that the combined increase in TRIB2 and MAP3K1 could be prognostic biomarkers and potential therapeutic targets for glioma." (PMID 31318172, 2020). "These novel findings indicated that TRIB2 and MAP3K1 could be potential predictors for evaluating the survival and efficacy of routine adjuvant treatments of glioma." (PMID 31318172, 2020). "Overall, these data suggest that enriched TRIB2 and MAP3K1, which could be used to predict the efficacy of routine adjuvant treatment for glioma, may indicate increased resistance to TMZ and radiotherapy." (PMID 31318172, 2020). "Seventeen glioma samples and three nontumor tissues were collected for RNA purification, and the expression levels of TRIB2 and MAP3K1 were evaluated by qRT‐PCR." (PMID 31318172, 2020). "Furthermore, to assess the prognostic roles of the combined expression of TRIB2 and MAP3K1 in glioma, we obtained the following four combinations using 91 tumor samples according to the IHC expression levels: TRIB2High/MAP3K1High, TRIB2High/MAP3K1Low, TRIB2Low/MAP3K1High, and TRIB2Low/MAP3K1Low." (PMID 31318172, 2020). "Similarly, we assessed the expression of TRIB2 and MAP3K1 in glioma/GBM by analyzing the TCGA (RNA sequencing) database, and the results demonstrated that TRIB2 and MAP3K1 were markedly increased in glioma tissues, especially GBM tissues, compared with nontumor tissues." (PMID 31318172, 2020). "In addition, we also detected the expression of Trib2 and Trib3 in the glioma cells, which was not altered by irradiation (data not shown)." (PMID 26521947, 2015). "The IHC results showed that TRIB2 was predominantly expressed in the nucleus, and MAP3K1 was enriched in the cytoplasm and cytomembrane of glioma cells, while no significant staining was observed in the nontumor tissues." (PMID 31318172, 2020). "The results showed a significant increase in TRIB2 and MAP3K1 in the glioma samples compared with the nontumor samples." (PMID 31318172, 2020).
lung adenocarcinoma (8 papers, 2012 to 2022). A carcinoma that arises from the lung and is characterized by the presence of malignant glandular epithelial cells. "miR-511, miR-1297 and let-7 inhibit proliferation in adenocarcinoma of lung by suppressing TRIB2 expression and consequently increasing C/EBPα expression." (PMID 34070799, 2021). "It has been reported that miR-206 and miR-140 act as tumour suppressor in lung adenocarcinoma by modifying oncogenic TRIB2 promoter activity." (PMID 34070799, 2021). "Specifically, miR-206 and miR-140 suppressed lung adenocarcinoma proliferation in vitro and in vivo by decreasing TRIB2 through Smad3 in TGF-β1 pathway." (PMID 28005074, 2016). "MiR-206 and miR-140 inhibited lung adenocarcinoma cell proliferation in vitro and in vivo by suppressing p-Smad3/Smad3 and TRIB2." (PMID 28005074, 2016). "In summary, miR-206 and miR-140, as tumor suppressors, induced lung adenocarcinoma cell death and inhibited cell proliferation by modifying oncogenic TRIB2 promoter activity through p-Smad3." (PMID 28005074, 2016). "The CCAAT/enhancer-binding proteins α and β (C/EBPα and β) are reported to be downstream factors of TRIB2.24, 25 To investigate the effects of Smad3-related miRNAs on C/EBPα and β expression, lung adenocarcinoma cells were treated with miR-140 and miR-206." (PMID 28005074, 2016). "In a previous study, we showed that TRIB2 was an oncogene, which was more highly expressed in lung adenocarcinoma compared with paracancerous tissue controls." (PMID 24137458, 2013). "As miRNAs to regulate TRIB2 expression, miR-511 and 1297 were further studied in lung adenocarcinoma tissue by real-time PCR." (PMID 23071539, 2012). "The oncogenic role of TRIB2 was further confirmed in our study, which showed increased levels of TRIB2 in human lung adenocarcinoma tissue." (PMID 23071539, 2012). "Additionally, we previously demonstrated that TRIB2 has an oncogenic role in lung adenocarcinoma, and miR-206 can modify TRIB2 promoter activity through p-Smad3." (PMID 35790734, 2022). "Similarly, miR-206 and miR-140 suppress lung adenocarcinoma cell proliferation and metastasis via reduced phospho-Smad3/Smad3, which downregulate TRIB2." (PMID 34070799, 2021). "As tumor suppressors, miR-206 and miR-140 can inhibit lung adenocarcinoma cell metastasis by increasing E-cadherin and decreasing α-SMA expression, and suppress lung adenocarcinoma cell growth in vivo by decreasing oncogenic TRIB2 promoter activity through Smad3." (PMID 28005074, 2016). "We measured Smad3 and TRIB2 expression in lung adenocarcinoma samples." (PMID 28005074, 2016). "Moreover, lung adenocarcinoma data supported a suppressive role for miR-206/miR-140 and an oncogenic role for TRIB2—patients with higher TRIB2 levels had poorer survival." (PMID 28005074, 2016). "The suppressive action of miRNA to tumorigenicity may be attributed to downregulation of TRIB2, which was supported by our previous study, demonstrating that lower levels of TRIB2 lead to inhibiting lung adenocarcinoma cell growth in vivo." (PMID 28005074, 2016). "miR-511 and miR-1297 act as tumor suppressor genes, which could suppress lung adenocarcinoma A549 cell line proliferation in vitro and in vivo by suppressing tribbles homolog 2 (TRIB2) gene and further increasing C/EBPα gene expression." (PMID 24913332, 2014). "The expression of miR-511/1297 was found to be lower in carcinoma than its control tissues, which indicated that these miRNAs might regulate TRIB2 in lung adenocarcinoma tissue." (PMID 23071539, 2012). "To determine whether miR-511 and 1297 could inhibit TRIB2 expression in another lung adenocarcinoma cell line, we studied the expression of GFP and TRIB2 in LTEP-a-2 cell line after miR-511/1297 treatment." (PMID 23071539, 2012).
lung adenocarcinoma (continued). "Considering the important roles of miRNAs in controlling cell differentiation as well as the oncogenic role of TRIB2, we speculated that TRIB2 expression may be altered by miRNAs and explored TRIB2- related miRNAs for lung adenocarcinoma therapy." (PMID 23071539, 2012). "By immunohistochemistry, we observed TRIB2 expression to be higher in human lung adenocarcinoma than in para-carcinoma tissue controls, supporting a possible oncogenic role for TRIB2 in the pathological changes of lung adenocarcinoma." (PMID 23071539, 2012). "We sought to determine whether TRIB2 plays an oncogenic role in the tumorigenesis of lung adenocarcinoma." (PMID 23071539, 2012). "For hsa-miR-511-3p, it has been reported to be related to lung adenocarcinoma by triggering BAX and TRIB2." (PMID 31105742, 2019).
osteosarcoma (6 papers, 2012 to 2023). A usually aggressive malignant bone-forming mesenchymal neoplasm, predominantly affecting adolescents and young adults. "The findings of a study on patients with osteosarcoma revealed that miR-509-5p acts as a tumor suppressor miRNA by targeting TRIB2 and can be considered as an inhibitory intervention in osteosarcoma." (PMID 35215154, 2022). "RNA-seq analysis showed that the transcriptional signature of the U2OS osteosarcoma cell line is altered by the overexpression of TRIB2 and exposure to the PI3K/mTOR inhibitor BEZ235." (PMID 33316942, 2020). "On the other hand, depletion of PRKAR2B, ADCK2, TRPM7, and TRIB2 significantly decreases the effect of TNFα on HIF-1α stability in osteosarcoma and prostate cancer cell lines." (PMID 22355351, 2012). "Further to this, using RNA sequencing-based transcriptional profiling of isogenic osteosarcoma U2OS cells with different TRIB2 status, a recent study identified several small-molecule compounds, including harmine and piperlongumine, that reverse TRIB2-dependent transcriptional signatures." (PMID 34070799, 2021). "To gain insight into the molecular mechanism by which TRIB2 mediates resistance, we analyzed global transcriptional changes using next-generation sequencing of total RNA (RNA-seq) in U2OS osteosarcoma cells, a cellular model which we have previously used to analyze the function of TRIB2." (PMID 33316942, 2020). "This screen determined that depletion of ADCK2, PRKAR2B, TRIB2 and TRPM7 most significantly downregulates nuclear accumulation of HIF-1α in response to the treatment of osteosarcoma cells." (PMID 22355351, 2012).
ovarian carcinoma (6 papers, 2018 to 2023). A malignant neoplasm originating from the surface ovarian epithelium. "In line with its downregulation in ovarian cancer cells, tumors from cisplatin-resistant patients also expressed the lowest levels of TRIB2." (PMID 35582723, 2019). "Conversely, in epithelial ovarian cancer, TRIB2 knockdown increases resistance to cisplatin." (PMID 34070799, 2021). "High levels of TRIB2 have been associated with drug resistance to standard therapies and PI3K inhibitors in a number of solid cancers, whereas low levels of TRIB2 expression have been associated with drug resistance in ovarian cancer patients." (PMID 29599919, 2018). "ISG15, SNCA, RIPK2, PLCG2, RHOU, TRIB2 and ELP2 influenced the OS and PFI of ovarian cancer patients in the TCGA-OV dataset, while RIPK2 also affected the OS and PFI of ovarian cancer patients treated with Taxol in the GSE30161, GSE32062 and GSE63885 datasets." (PMID 35477477, 2022). "One possible explanation for the TRIB2 knockdown-dependent cisplatin resistance may be due to the subsequent activation of FOXO proteins, since it has been reported that the levels of FOXO proteins are related to cisplatin resistance in ovarian cancer." (PMID 34070799, 2021).
hepatocellular carcinoma (5 papers, 2016 to 2025). A malignant tumor that arises from hepatocytes. "Recent work in liver fibrosis and hepatocellular carcinoma (HCC) has demonstrated that TRIB2 is strongly upregulated in human fibrotic liver tissues and HCC tissues." (PMID 34070799, 2021). "In the hepatocellular carcinoma context, TRIB2 has been shown to be a downstream effector and upstream regulator of Wnt signalling." (PMID 34070799, 2021). "More specifically in hepatocellular carcinoma Bel-7402 cells, TRIB2 instability requiresβTRCP and total levels are under the regulation of CUL1." (PMID 27019349, 2016). "Thus, they elucidated a novel role for TRIB2 in desensitizing ferroptosis via E3 βTrCP, by which it promotes Tfrc ubiquitination and ultimately reduces labile iron in hepatoma cells." (PMID 36110200, 2022). "Studies suggest that TRIB2 overexpression negatively regulates the activity of the WNT signaling pathway and inhibits WNT-mediated transcriptional activity in hepatocellular carcinoma (HCC), which is closely related to patient prognosis." (PMID 39963268, 2025).
narcolepsy (5 papers, 2012 to 2023). A sleep disorder characterized by a tendency for excessive sleepiness during the day which occurs even after adequate sleep in the nighttime. "We also showed that a passive transfer of anti-TRIB2 IgG autoantibodies, isolated from patients with narcolepsy, induced neural loss and sleep attacks in mice." (PMID 37296631, 2023). "In addition to a strong association especially with HLA DQB1*0602/DRB1*15/DR15 – DQ6 HLA type, narcolepsy has been associated with the presence of TRIB-2 antibodies, specific T-cell receptor alpha, and purinergic receptor P2RY11 genotypes." (PMID 22470463, 2012). "Previous research reports have supported the hypothesis that there are low levels of serum TRIB2 autoantibodies in HLA-DQB1*06:02-positive young narcolepsy patients with cataplexy, which they linked to influenza pandemic vaccination and A/H1N1 antibodies in 2009." (PMID 36358399, 2022). "In mice with passively transferred TRIB2 autoantibodies, narcolepsy with cataplexy phenotype can be seen." (PMID 36358399, 2022). "In contrast, several studies have discovered that the TRIB-2 protein (tribbles homolog 2), which is produced by many cells including hypocretin neurons, is a putative target for autoantibodies in narcolepsy patients with cataplexy one year after onset." (PMID 36358399, 2022). "The authors went on to demonstrate increase Trib2 autoantibodies in recent onset narcolepsy cases, a result that was replicated by our group and a Japanese study using sera samples from subjects collected in the 1990–2000s, and some cross-reactivity of sera with hypocretin neurons." (PMID 24825774, 2014). "Pursuing this line of investigation, we also found that TRIB2 autoantibodies were generally absent in more recent narcolepsy samples." (PMID 24825774, 2014). "It is our hypothesis that TRIB2 autoantibodies may have marked a coinfection present together with a narcolepsy trigger in some cases with onset notably in the 1990s and 2000s, a result substantiated by the finding of a correlation between A/H1N1 and TRIB2 autoantibody levels in a recent study." (PMID 24825774, 2014).
Obesity (4 papers, 2014 to 2024). Accumulation of substantial excess body fat. "The obesity-resistance-associated allele of TRIB2 underwent positive natural selection in East Asians during the last glacial maximum, suggesting that this TRIB2 variant links past adaptation to present resistance to obesity." (PMID 28212671, 2017). "An obesity-related single-nucleotide polymorphism (SNP) of the Tribbles pseudokinase 2 gene (TRIB2) was shown to have underwent adaptive evolution in the last glacial period, suggesting a selective advantage of this SNP in human populations in cold environments." (PMID 28212671, 2017). "Similarly, introducing Trib2 specifically into the liver of mice also leads to insulin resistance, and systemic and liver-specific deficiency of Trib2 protects mice against diet-induced obesity with improved insulin sensitivity and glucose homeostasis." (PMID 39623091, 2024). "Both of the SNPs that we found to be associated with higher TRIB2 mRNA levels as well as sleep duration and obesity (rs72773697 and rs17390839) are located outside of the TRIB2 gene locus." (PMID 37083954, 2023).
breast carcinoma (3 papers, 2016 to 2023). "LncRNA MEG3 regulates chondrogenic differentiation by inhibiting TRIB2, which is achieved by binding with EZH2 as well as LINC02273; it is associated with hnRNPL, which promotes metastasis of breast cancer by increasing AGR2 transcription." (PMID 38017487, 2023).
cervical carcinoma (3 papers, 2013 to 2017). A carcinoma arising from either the exocervical squamous epithelium or the endocervical glandular epithelium. "However, the biological role of TRIB2 in cervical carcinoma remains unclear." (PMID 24137458, 2013).
prostate carcinoma (3 papers, 2012 to 2025). A carcinoma that arises from epithelial cells of the prostate gland. "Recent data indicate that TRIB2 is particularly overexpressed in enzalutamide-resistant and neuroendocrine (NE) prostate cancer, a major contributor to prostate cancer morbidity and mortality." (PMID 39520729, 2025). "In this study, we report our efforts to develop the first examples of TRIB2 degrader, which exhibits potent degradation activity and significant cell growth inhibitory effects against prostate cancer cells." (PMID 39520729, 2025). "Among these compounds, 5k demonstrated potent TRIB2 degradation with a DC50 value of 16.84 nM (95% CI: 13.66 – 20.64 nM) in prostate cancer PC3 cells." (PMID 39520729, 2025). "In DU145 cells, a prostate cancer cell line with moderate invasive potential, only TRIB2 depletion was effective in abrogating TNFα-induced HIF-1α accumulation." (PMID 22355351, 2012). "Inhibition of TRIB2 has been shown to resensitize resistant prostate cancer cells to enzalutamide." (PMID 38794149, 2024).
alcohol dependence (2 papers, 2020). Physical and psychological dependence on alcohol. "Enrichment analysis of the list of TRIB2 upregulated transcripts showed a significant enrichment for genes involved in pathways in cancer and TNF signaling, alcoholism and transcriptional misregulation in cancer." (PMID 33316942, 2020).
autoimmune uveitis (2 papers, 2007 to 2013). An autoimmune form of uveitis (disease). "Recently, the transcript encoding Tribbles homolog 2 (Trib2), an autoantigen in autoimmune uveitis, was reported to be enriched in orexin neurons, and has been considered as a possible candidate antigen responsible for the autoimmunity." (PMID 23616752, 2013). "TRIB2 (tribbles homolog 2) was identified as an autoantigen in autoimmune uveitis, a term encompassing a group of ocular inflammatory disorders with unknown causes." (PMID 17915034, 2007).
chronic myeloid leukemia (2 papers, 2021 to 2025). "It promotes proliferation and inhibits apoptosis in AML and chronic myeloid leukemia (CML) cells by targeting CTDSPL and TRIB2." (PMID 40161350, 2025).
esophageal squamous cell carcinoma (2 papers, 2022 to 2024). Esophageal squamous cell carcinoma (ESCC) is a type of esophageal carcinoma (EC) that can affect any part of the esophagus, but is usually located in the upper or middle third. "Liu and his team identified a crucial regulatory METTL14-miR99a-5p-TRIB2 feedback circuit that promoted cancer stemness and radioresistance in esophageal squamous cell carcinoma (ESCC)." (PMID 36517820, 2022).
inflammatory bowel disease (2 papers, 2021 to 2023). A spectrum of small and large bowel inflammatory diseases of unknown etiology. "In inflammation TRIB2 has been described as a regulator of NF-κB activity associated with inflammatory bowel disease (IBD), and TRIB2 inhibits TLR5-mediated activation of NF-κB." (PMID 34070799, 2021). "In inflammatory bowel disease, the active inflamed tissue exhibits reduced Trib2 (TRIB2) expression, and Trib2 inhibits NF-κB activation mediated by Toll-like receptor 5 (TLR5)." (PMID 36979341, 2023).
pancreatic cancer (2 papers, 2021). "Recent evidence suggests that ZEB1-AS1 as a long non-coding RNA (lncRNA) by regulating miR-505-3p/TRIB2 axis enhances the growth, viability, and invasion of pancreatic cancer cells." (PMID 33794905, 2021).
acute leukemia (1 paper, 2017). A clonal (malignant) hematopoietic disorder with an acute onset, affecting the bone marrow and the peripheral blood. "This new observation is intriguing but biologically plausible in view of the existing literature on the oncogenic role of TRIB2 in acute leukemia and other malignancies." (PMID 29312632, 2017).
anaplastic astrocytoma (1 paper, 2024). "Through a comparative analysis of the different histologies of brain tumors, we detected that TRIB2 had higher levels in anaplastic astrocytoma and GB than the other histologies." (PMID 38794149, 2024).